NLN (neurolysin)
Description:
Hydrolyzes oligopeptides such as neurotensin, bradykinin and dynorphin A (By similarity). Acts as a regulator of cannabinoid signaling pathway by mediating degradation of hemopressin, an antagonist peptide of the cannabinoid receptor CNR1 (By similarity).
Synonyms: MEP; AGTBP; KIAA1226; EP24.16; MOP
Tractability: Small molecule: a high-quality ligand is known. Antibody: its Gene Ontology location is reachable by antibodies, with high confidence. PROTAC: ubiquitination databases record sites on it; its protein half-life has been measured; a small molecule that binds it is known.
Target class: Enzyme; Hydrolase
Gene: Protein-coding gene on chromosome 5 (65,722,205 to 65,871,725, forward strand). Ensembl gene ENSG00000123213.
Subcellular location: Mitochondrion intermembrane space; Cytoplasm, cytosol
Subcellular location (Human Protein Atlas): Mitochondria
Pathways (Reactome):
Signal Transduction: Peptide ligand-binding receptors
Gene Ontology:
Molecular function: endopeptidase activity; metalloendopeptidase activity; metallopeptidase activity; peptidase activity; peptide binding
Biological process: G protein-coupled receptor signaling pathway; proteolysis
Cellular component: mitochondrion; extracellular region; mitochondrial intermembrane space; mitochondrial matrix; cytosol; plasma membrane
Genetic constraint (gnomAD): Loss-of-function variants: 36 observed, 50.88 expected, observed/expected ratio (o/e) 0.71, 90% interval 0.54 to 0.93. The upper end of that interval is the gene's LOEUF score, 0.93, which puts it in group 3 of 6, group 1 being the genes least tolerant of losing a copy. Missense variants: 590 observed, 614.41 expected, observed/expected ratio (o/e) 0.96, 90% interval 0.9 to 1.03. Synonymous variants: 202 observed, 219.29 expected, observed/expected ratio (o/e) 0.92, 90% interval 0.82 to 1.03.
Homologues: Orthologues: chimpanzee NLN (99% identical), macaque NLN (98% identical), dog NLN (94% identical), pig NLN (94% identical), guinea pig NLN (92% identical), rabbit NLN (90% identical), mouse Nln (90% identical), rat Nln (90% identical), tropical clawed frog nln (67% identical), zebrafish nln (57% identical), Drosophila melanogaster CG11771 (20% identical), Caenorhabditis elegans eelo-2 (18% identical). Paralogues in human: THOP1 (61% identical), MIPEP (25% identical).
Diseases named in the same sentence as NLN in open-access papers:
NLN is named in the same sentence as 21 diseases in open-access papers, as found by Europe PMC text mining. Sharing a sentence is not in itself a finding about the gene and the disease. The quoted sentences say what the papers report.
acute myeloid leukemia (2 papers, 2020 to 2025). Acute myeloid leukemia (AML) is a group of neoplasms arising from precursor cells committed to the myeloid cell-line differentiation. "While NLN is recognized for its oncogenic role in acute myeloid leukemia (AML), its involvement in solid tumors, including lung cancer, has not been extensively studied." (PMID 41242017, 2025). "Recently, the mitochondrial proteases caseinolytic protease P (CLPP) and neurolysin (NLN) have been identified as therapeutic targets in acute myeloid leukemia (AML)." (PMID 32761807, 2020). "The compound 3-[(2S)-1-[(3R)-3-(2-Chlorophenyl)-2-(2-Fluorophenyl)pyrazolidin-1-yl]-1 -oxopropan-2-yl]-1-(adamantan-2-yl) urea, referred to as Neurolysin-R2 (NR2), is an allosteric inhibitor of NLN that has been shown to inhibit the proliferation of acute myeloid leukemia (AML) cells in vitro." (PMID 41242017, 2025). "The mitochondrial proteases neurolysin (NLN) and caseinolytic protease P (CLPP) have been identified as therapeutic targets in acute myeloid leukemia (AML)." (PMID 32761807, 2020). "Recent studies have begun to elucidate its involvement in cancer, particularly in hematological malignancies such as acute myeloid leukemia (AML), where NLN has been demonstrated to support tumor viability by regulating the formation of mitochondrial respiratory chain supercomplexes." (PMID 41242017, 2025). "More recent research has highlighted the necessity of NLN for the growth of leukemic cells and progenitors, with NLN knockdown impairing the formation of respiratory chain supercomplexes (RCS), which are crucial for oxidative phosphorylation in acute myeloid leukemia(AML)." (PMID 41242017, 2025).
breast carcinoma (2 papers, 2016 to 2021). "Knockdown of CCND1, PLAU, SEPN1, and NLN suppressed cell growth, similar to miR-193a-5p and miR-193a-3p overexpression in breast cancer cells." (PMID 27307030, 2016). "MiR-193a-5p suppressed cell growth by repressing NLN in breast cancer." (PMID 27307030, 2016). "MiR-193a-5p significantly silenced the expression of the NLN protein in breast cancer cells." (PMID 27307030, 2016). "In summary, NLN expression was directly regulated by miR-193a-5p, and CCND1, PLAU, and SEPN1 expression was directly regulated by miR-193a-3p in breast cancer cells." (PMID 27307030, 2016). "Furthermore, NLN and CCND1, PLAU, and SEPN1 were directly targeted by miR-193a-5p and miR-193a-3p, respectively, in breast cancer cells." (PMID 27307030, 2016).
essential hypertension (2 papers, 2015 to 2021). Hypertension that presents without an identifiable cause. "For example, TH was related to essential hypertension; DRD2 to childhood temperament, extraversion, and antisocial behavior; and neurotensin genes (NLN, NTSR1, NTRS2) to schizophrenia and memory consolidation." (PMID 26308205, 2015).
Alzheimer disease (1 paper, 2021). A progressive, neurodegenerative disease characterized by loss of function and death of nerve cells in several areas of the brain leading to loss of cognitive function such as memory and language. "In terms of neurodegenerative diseases, one of the causes of Alzheimer’s disease is a mutation that causes increased β-amyloid, and neurolysin is a β-amyloid peptide-degrading enzyme." (PMID 33468232, 2021).
hypertensive encephalopathy (1 paper, 2014). Encephalopathy resulting from hypertension. "Ang II can damage the blood-brain barrier leading to hypertensive encephalopathy; this effect could be exacerbated by the loss of its metabolic inactivation by neurolysin." (PMID 25147932, 2014).
lung adenocarcinoma (1 paper, 2025). A carcinoma that arises from the lung and is characterized by the presence of malignant glandular epithelial cells. "Further comparative analysis of paired samples revealed a significant upregulation of NLN protein expression in both lung adenocarcinoma and squamous cell carcinoma." (PMID 41242017, 2025). "The staining intensity was scored, revealing that NLN expression was significantly elevated in both lung adenocarcinoma and lung squamous cell carcinoma tissues compared to normal lung tissues." (PMID 41242017, 2025). "Additionally, utilizing data from The Cancer Genome Atlas (TCGA), we observed that NLN is also highly expressed at the mRNA level in lung adenocarcinoma and squamous cell carcinoma." (PMID 41242017, 2025). "Expression analysis across different stages of lung cancer progression using TCGA data indicated that NLN is significantly upregulated in stage I of both lung adenocarcinoma and squamous cell carcinoma, with a trend of increasing expression as the stage advances in lung adenocarcinoma." (PMID 41242017, 2025).
lung carcinoma (1 paper, 2025). "Given its mitochondrial localization and known functions in regulating cellular metabolism, NLN could be implicated in the modulation of ferroptosis, a hypothesis that has yet to be explored in the context of lung cancer." (PMID 41242017, 2025). "Through Transwell assays, we observed that the suppression of NLN expression significantly attenuated the metastatic potential of lung cancer cells." (PMID 41242017, 2025). "Collectively, all of these findings confirm that the knockdown of NLN induces ferroptosis in lung cancer cells." (PMID 41242017, 2025). "Currently, there is a lack of research concerning the regulation of ferroptosis by NLN, rendering this study a pioneering effort in elucidating NLN's role in the modulation of ferroptosis within the context of lung cancer." (PMID 41242017, 2025). "We next evaluated the expression levels of NLN in various lung cancer cell lines through quantitative reverse transcription polymerase chain reaction (qRT-PCR) and Western blot analysis." (PMID 41242017, 2025). "We demonstrated that NLN expression was significantly upregulated in lung cancer tissues relative to adjacent normal tissues." (PMID 41242017, 2025). "This study is the first to demonstrate that the inhibition of NLN induces ferroptosis in lung cancer cells, elucidating the regulation of GPX4 expression by m6A modification and enriching the complexity of the ferroptosis regulatory network." (PMID 41242017, 2025). "Following the determination that NLN knockdown induces ferroptosis in lung cancer cells, we sought to elucidate the potential mechanisms by which NLN regulates this process." (PMID 41242017, 2025). "Further statistical analysis revealed that NLN levels were significantly elevated in early-stage (stage I) lung cancer, aligning with the results obtained from TCGA data analysis." (PMID 41242017, 2025). "By elucidating the mechanisms through which NLN influences ferroptosis, this study aims to provide new insights into the metabolic vulnerabilities of lung cancer and identify NLN as a potential therapeutic target." (PMID 41242017, 2025). "Our findings identified GPX4 as the most critical downstream factor involved in NLN-induced ferroptosis in lung cancer cells, with its expression significantly suppressed following NLN knockdown." (PMID 41242017, 2025). "In this study, we investigate the role of NLN in lung cancer, specifically focusing on its potential involvement in the regulation of ferroptosis." (PMID 41242017, 2025). "To confirm that the cell death induced by NLN knockdown is indeed ferroptosis rather than another form of cell death, we assessed the sensitivity of lung cancer cells to RSL3-induced ferroptosis following NLN suppression." (PMID 41242017, 2025). "This suggests that NLN, as a potential therapeutic target for non-small cell lung cancer, may enhance efficacy or address drug resistance issues by inducing ferroptosis in lung cancer." (PMID 41242017, 2025). "By leveraging the prognostic information from this cohort alongside data from The Cancer Genome Atlas (TCGA), Kaplan-Meier survival analysis indicated that high expression levels of NLN are significantly correlated with poor prognosis in lung cancer (P < 0.001)." (PMID 41242017, 2025). "More notably, inhibition of NLN induced ferroptosis in lung cancer cells." (PMID 41242017, 2025). "We further investigated the mechanism by which NLN exerts its oncogenic function in lung cancer." (PMID 41242017, 2025). "Depletion of NLN inhibits m6A modification of GPX4 mRNA, leading to degradation of GPX4 mRNA, leading to ferroptosis in lung cancer cells." (PMID 41242017, 2025).
lung carcinoma (continued). "Additionally, we elucidated the specific molecular mechanism by which NLN induces ferroptosis in lung cancer cells: the knockdown of NLN inhibits the m6A modification of GPX4 mRNA, leading to the degradation of GPX4 mRNA and subsequently triggering ferroptosis in lung cancer cells." (PMID 41242017, 2025).
melanoma (1 paper, 2007). A malignant, usually aggressive tumor composed of atypical, neoplastic melanocytes. "The complete sequencing of neurolysin cDNA from melanoma showed three modifications in relation to the mouse gene: thymine 666 to cytosine, thymine 1268 to cytosine and thymine 1316 to cytosine." (PMID 17620116, 2007). "Using specific antibodies against the studied oligopeptidases, we showed that TOP activity in melanoma cells is significantly greater than that of neurolysin." (PMID 17620116, 2007). "The presence of TOP and neurolysin in melanoma cells and culture supernatants was confirmed by hydrolytic assays and by cloning and sequencing the corresponding cDNAs from B16F10-Nex2 cells." (PMID 17620116, 2007). "The specific anti-TOP antibody inhibited 80% of the B16F10-Nex2 catalytic activity, using the FRET peptide Abz-GFSPFRQ-EDDnp, whereas the anti-neurolysin antibody inhibited only 20% of the melanoma enzyme activity." (PMID 17620116, 2007). "The melanoma neurolysin gene showed three modifications in relation to mouse gene sequence, but only two changes promoted substitutions in the amino acid sequence away from the conserved Zn-binding catalytic site (HEFGH) or from other amino acids described as important to enzyme activity." (PMID 17620116, 2007). "Melanoma supernatant hydrolyzed these substrates as the recombinant TOP and neurolysin do, indicating that the melanoma peptidase activities could be related to these enzymes." (PMID 17620116, 2007). "In addition, the enzymes of the melanoma supernatant hydrolyzed the substrate Abz-GFSPFRQ-EDDnp at the Pro-Phe bond as described for TOP and neurolysin, indicating that the melanoma activity had the same specificity as of the recombinant mouse enzymes." (PMID 17620116, 2007). "Thimet oligopeptidase (TOP) and neurolysin activities were then investigated in B16F10-Nex2 melanoma cells aiming at gene sequencing, enzyme distribution and activity, influence on tumor development, substrate specificity, hydrolytic products and susceptibility to inhibitors." (PMID 17620116, 2007). "Both melanoma enzyme cDNAs were cloned, confirming the presence of TOP and neurolysin in melanoma cells, and the gene and translated protein sequences were compared to the mouse sequences (data not shown)." (PMID 17620116, 2007). "The complete inhibition of melanoma peptidase by o-phenanthrolin as well as by JA-2, and the partial inhibition by Pro-Ile give support to the functional similarity of melanoma enzymes with the oligopeptidases TOP and neurolysin." (PMID 17620116, 2007). "Incubation of NT with melanoma supernatant resulted in the generation of NT1–8 and NT1–10, the same N-terminal fragments generated respectively by cleavage of NT by TOP and neurolysin, that were identified by mass spectrometry." (PMID 17620116, 2007). "The melanoma supernatant was able to cleave all the assayed substrates, except Abz-GFPPFRQ-EDDnp and Abz-rRL-EDDnp, which were also resistant to recombinant TOP and neurolysin." (PMID 17620116, 2007).
α-synucleinopathies (1 paper, 2024). "Collectively, our results suggest that enhancing the level of NLN rescues defects caused by synucleinopathy in yeast, human cells, and mouse primary neurons." (PMID 38906862, 2024). "Therefore, the reduced expression of Neurolysin in DA neurons may explain the DA neuron-specific toxicity of α-synucleinopathies and mitochondrial dysfunction in PD." (PMID 38906862, 2024).
tumor (3 papers, 2007 to 2025). "Immunohistochemical staining was conducted on subcutaneous tumor tissues from both the control group (sh-Ctrl) and the NLN knockdown group (sh-NLN)." (PMID 41242017, 2025). "The results demonstrated a significant reduction in NLN expression levels within the tumor tissues of the sh-NLN group, indicating that the observed attenuation in tumor growth is likely a result of NLN suppression." (PMID 41242017, 2025). "Consistent with the in vitro results, a reduction in tumor burden was observed following the knockdown of NLN." (PMID 41242017, 2025). "In vivo studies confirmed that the suppression of NLN significantly inhibited tumor growth in a mouse model." (PMID 41242017, 2025). "Moreover, we developed a specific small molecule inhibitor, NR2, which targets NLN and induces tumor cell death both in vitro and in vivo, showcasing potent anti-tumor activity." (PMID 41242017, 2025). "The secretion of both enzymes, TOP and neurolysin, might, however, influence tumor growth in vivo by affecting angiogenesis." (PMID 17620116, 2007). "To further investigate the tumorigenic function of NLN in vivo, we established a doxycycline (DOX)-inducible conditional NLN knockdown cell model, A549-Tet-shNLN, and conducted subcutaneous xenograft tumor experiments in nude mice." (PMID 41242017, 2025). "To directly kill tumor cells, we exploited KLAKLAKKLAKLAK (named KLA), a pro-apoptotic peptide, and synthesized hybrid peptides consisting of either NLN or NEW and KLA (named NLN-KLA and NEW-KLA, respectively)." (PMID 33391537, 2021). "In this study, we identify NLN may play a role in regulating ferroptosis in certain NSCLC cell models, offering new insights into mitochondrial peptidases in tumor biology." (PMID 41242017, 2025).
cancer (1 paper, 2021). A tumor composed of atypical neoplastic, often pleomorphic cells that invade other tissues. "Of note, this study for the first time revealed that the dysregulation of MAPK1, ACOX1, SCP2, and NLN is significantly correlated to the survival time in EC patients, whose functional importance had been implied in multiple cancer types." (PMID 34124063, 2021).
cardiovascular diseases (1 paper, 2023). "Notably, mRNAs for most genes associated with cardiovascular diseases (e.g., HSD3B2, PPARG, NLN and CEACAM1) were downregulated in the colons of HBP subjects." (PMID 36768972, 2023).
NLN also shares sentences with these, for which no sentence is quoted: aortic valve disease (1 paper); COVID-19 (1); Hypertension (1); lung squamous cell carcinoma (1); neurodegenerative disease (1); non-small cell lung carcinoma (1); Obesity (1); schizophrenia (1); squamous cell carcinoma (1).